IL4 (interleukin 4)
Diseases named in the same sentence as IL4 in open-access papers (continued):
Sharing a sentence is not in itself a finding about the gene and the disease.
chronic gastritis (1 paper, 2020). Inflammation of the stomach that is chronic in nature. "IL-8 leads to the migration of neutrophils and monocytes into the mucosa; the activated monocytes and dendritic cells stimulate the production of various cytokines, such as IL-4, IL-5, IL-6 and interferon-γ (IFN-γ), leading to an inflammatory reaction (chronic gastritis)." (PMID 32403331, 2020).
chronic hepatitis (1 paper, 2020). An active inflammatory process affecting the liver for more than six months. "A causal link has been established between aberrant levels of IL-4 and IL-6 and alcohol-induced hepatitis, primary biliary cirrhosis, and chronic hepatitis in humans." (PMID 31998436, 2020).
chronic thromboembolic pulmonary hypertension (1 paper, 2024). Chronic thromboembolic pulmonary hypertension (CTEPH) is characterized by the persistence of thromboemboli in the form of organized tissue obstructing the pulmonary arteries. "Also, in patients with chronic thromboembolic pulmonary hypertension (CTEPH), different cytokines showed increased levels, such as IL-1β, IL-2, IL-4, IL-6, IL-8 and IL-10." (PMID 38612795, 2024).
chronic widespread pain (1 paper, 2019). Chronic pain that is felt all over the body. "Comparable results indicating lowered levels of anti-inflammatory cytokines were reported in a study that examined IL-4 and IL-10 gene expression patterns and serum concentrations in chronic widespread pain patients including FM." (PMID 31470635, 2019).
Cluster headache (1 paper, 2017). A type of headache characterized by repeated attacks of unilateral pain lasting 15 to 180 minutes and associated with local autonomic signs. "These analyses suggest that inter- and intracellular signalling pathways involving brain-related molecules (e.g. GABA and ion channels) and inflammation-related molecules (e.g. CD28 and interleukin-4 (IL-4)), metabolism and oxidation might be involved in cluster headache." (PMID 28074859, 2017).
CNS lymphoma (1 paper, 2013). "As CNS lymphoma microenvironment is rich in IL-4 and as IL-4 is known to induce M2 polarization of macrophages, IL-4 treatment followed by DMSO or POM treatment was tested on U937, primary microglial cells, and primary peritoneal macrophages." (PMID 23940785, 2013). "It has been shown that macrophages in PCNSL are M2 polarized related to upregulation of IL4 in CNS lymphoma." (PMID 23940785, 2013).
colorectal adenocarcinoma (1 paper, 2021). The most common type of colorectal carcinoma. "In human monocytes, adenocarcinoma human alveolar basal epithelial cells (A549 cell line), and human colorectal adenocarcinoma cells (Caco2 cell line), 15-LOX expression level was induced following treatment with interleukin 4 (IL4)." (PMID 34838055, 2021).
colorectal polyps (1 paper, 2019). "Recent studies have found that IL-4 levels in colorectal polyp-derived serum were significantly higher than those in serum from healthy volunteers." (PMID 30883594, 2019).
common variable immunodeficiency (1 paper, 2012). "A bias towards Th2-mediated immune response was also documented in patients with common variable immunodeficiency (CVID) through investigation of cytokine levels and demonstration of increased IL-4 and IL-10 production." (PMID 21918651, 2012).
cryptosporidiosis (1 paper, 2024). Intestinal infection with organisms of the genus Cryptosporidium. "In contrast, cryptosporidiosis caused significant elevations in the levels of the assessed cytokines (IFN-γ and IL-4)." (PMID 39507782, 2024). "IL-4 and IFN-γ have a synergistic effect in alleviating cryptosporidiosis." (PMID 39507782, 2024).
cystinosis (1 paper, 2019). Cystinosis is a metabolic disease characterized by an accumulation of cystine inside the lysosomes, causing damage in different organs and tissues, particularly in the kidneys and eyes. "Here, we explored if macrophage polarization to either proinflammatory M1-like M(LPS/IFNγ) or anti-inflammatory M2-like M(IL-4/IL-10) affected TNT-like protrusion formation, intercellular transport and, ultimately, the efficacy of cystinosis prevention." (PMID 31601865, 2019).
cystitis (1 paper, 2019). Inflammation of the urinary bladder. "We previously showed that a single dose of IPSE (Interleukin-4-inducing principle from Schistosoma eggs), a schistosome-derived host modulatory protein, can ameliorate ifosfamide-related cystitis; however, the mechanisms underlying this urotoxicity and its prevention are not fully understood." (PMID 30733505, 2019).
Darier disease (1 paper, 2025). Darier disease (DD) is a keratinization disorder characterized by the development of keratotic papules in seborrheic areas and specific nail anomalies. "Dupilumab, a monoclonal antibody targeting IL-4 and IL-13, has shown excellent efficacy in alleviating pruritus in other dermatologic conditions and may also help manage itch in patients with Darier disease, as evidenced by a recent case report." (PMID 40142630, 2025).
diabetic foot ulcers (1 paper, 2022). "Increased serum levels of IL-10, IL-6, IFN-γ, IL-4 and adiponectin have been shown in patients with diabetic foot ulcers treated with hyperbaric oxygen." (PMID 36198698, 2022).
Diffuse Systemic Sclerosis (1 paper, 2023). "Romilkimab, an anti-IL-4 and anti-IL-13 antibody, has shown promising results in animal models and is currently undergoing Phase II trials (Effectiveness and Safety of SAR156597 in Treating Diffuse Systemic Sclerosis, NCT02921971)." (PMID 37035331, 2023).
dilatation (1 paper, 2022). "Collectively, these results are consistent in showing that the combined cardiac overexpression of IL9, IL3, IL4, IL13, and IL15 during the chronic phase of CVB3-induced VM can significantly improve the outcome of cardiac disease, reducing cardiac dilatation and dysfunction." (PMID 35508525, 2022).
disseminated candidiasis (1 paper, 2012). Systemic candidiasis occurs when Candida yeast enters the bloodstream and may spread (becoming disseminated candidiasis) to other organs, including the central nervous system, kidneys, liver, bones, muscles, joints, spleen, or eyes. "In addition, Th2 responses, indicated by high levels of IL-4, are detrimental to a host/patient with disseminated candidiasis." (PMID 23144764, 2012).
DRESS syndrome (1 paper, 2022). "Interleukin (IL)-17 is overexpressed in DRESS syndrome, including IL-17E, which can further raise circulating eosinophils, eotaxin, IL-4 level, IL-5 level, and IgE, thereby enhancing the eosinophilic immune response." (PMID 36059007, 2022).
dysentery (1 paper, 2022). Acute inflammation of the intestine associated with infectious diarrhea of various etiologies, generally acquired by eating contaminated food containing toxins, biological derived from bacteria or other microorganisms. "The presence of IL-1β, IL-4, IL-16, and tumor necrosis factor beta (TNF-β) was associated with the absence of dysentery." (PMID 35924851, 2022). "Increased levels of GM-CSF and reduced production of TNF-β, IL-1β, IL-17A, IL-16, IL-4, and IL-10 were distinct responses observed in Shigella-infected children with dysenteric diarrhea compared to Shigella without dysentery." (PMID 35924851, 2022). "Children with dysenteric Shigella had lower levels of IL-16, IL-4, and IL-10 in their stools than children with Shigella without dysentery after adjustment for age and sex (blue circles)." (PMID 35924851, 2022). "Comparison of the response ratios of cytokines that were significantly different between children with and without dysentery confirmed that dysenteric Shigella was associated with >4-fold-higher levels of GM-CSF and reduced production of TNF-β, IL-1β, IL-16, and IL-4." (PMID 35924851, 2022).
dysplasia (1 paper, 2016). A usually neoplastic transformation of the cell, associated with altered architectural tissue patterns. "We observed increases of CD4+ T-cells, Foxp3+ T-lymphocytes, CD68+ macrophages, and IL-4+ cells during the progression of dysplasia in OLK and a parallel decrease in the expression of the inflammatory cytokine IFN-γ." (PMID 28053372, 2016). "OSCC had significantly more IL-10+, but not more IL-4+ cells, than OLP and OLK tissues, while the number of IL-4+, but not IL-10+ cells, increased gradually with the progression of dysplasia in OLK tissue." (PMID 28053372, 2016).
edema (1 paper, 2026). An abnormal accumulation of fluid beneath the skin, or in one or more cavities of the body. "We found that AA treatment significantly alleviated radiation-induced lung histopathological damage, reduced inflammatory cytokines IL-1β, IL-4, IL-6, IFN-γ in BALF, mitigated oxidative stress, and improved pulmonary edema and overall health status." (PMID 41564102, 2026).
endometritis (1 paper, 2025). An acute or chronic, usually bacterial infectious process affecting the endometrium. "It is possible that TNF-α, IL-1β, IL-4 and IL-10 significantly generated during endometritis, by increasing the viability of stromal cells, may affect the regeneration of endometrial cells damaged by inflammation." (PMID 39843578, 2025).
epistaxis (1 paper, 2022). Bleeding from the nose. "The serum levels of IL-4, IL-10, IL-17A, IL-23, and IFN- were evaluated in 90 patients with idiopathic epistaxis and 90 healthy controls using enzyme-linked immunosorbent assay (ELISA) technique." (PMID 35145935, 2022). "In the present study, IL-17A, IL-23, IFN-γ, IL-4, and IL-10 serum levels were compared between patients with idiopathic epistaxis and normal controls." (PMID 35145935, 2022). "Therefore, the IFN-, IL-4, and IL-10 serum levels were also determined in patients with epistaxis in comparison with healthy controls." (PMID 35145935, 2022). "Nonetheless, IL-17A (P=0.325), IL-23 (P=0.930), IFN- (P=0.860), IL-4 (P=0.313), and IL-10 (P=0.158) serum levels did not change in epistaxis patients with and without a familial history of epistaxis." (PMID 35145935, 2022). "Furthermore, IL-17A (P= 0.760), IL-23 (P=0.658), IFN- (P=0.961), IL-4 (P=0.370), and IL-10 (P=0.487) serum levels did not change in female and male patients with epistaxis." (PMID 35145935, 2022).
Epstein-Barr virus infection (1 paper, 2015). An infection that is caused by Epstein-Barr virus. "Taken together, it is necessary to consider the possibility that defective development of IL-4-induced innate CD8+ T cells causes the heighten susceptibility to Epstein-Barr virus infection in XLP patients." (PMID 26452143, 2015).
equine disease (1 paper, 2019). "The future experiments may be designed to determine the immune modulating activity of recombinant horse IL-4 and IL-10 in equine disease model." (PMID 31190704, 2019).
erythroderma (1 paper, 2025). "Erythroderma is considered a Th2‐type cytokine dominant condition, and IL‐4 and IL‐13 are implicated to play important roles in the etiology of erythroderma." (PMID 39526626, 2025). "Therapies targeting Th2 type molecules, IL‐4 and IL‐13, may be expected for refractory erythroderma, although such therapies should be applied to idiopathic erythroderma after malignancies are excluded." (PMID 39526626, 2025). "The etiology of erythroderma is suggested to be a Th2‐dominant condition with IL‐4/IL‐13 playing a central role, suggesting that therapies targeting those Th2 molecules may result in sufficient effects." (PMID 39526626, 2025).
esophageal tumor (1 paper, 2018). "By contrast, the esophageal tumor size and serum levels of IL-1β, IL-4, IL-13 and tumor necrosis factor-alpha (TNF-α) were not significantly affected by adding açaí to the diet for 35 weeks." (PMID 29966007, 2018).
Eustachian tube obstruction (1 paper, 2024). "Therefore, by reducing IL-4 and/or IL-13 levels, Dupilumab may inhibit periostin production, thus suppressing inflammation, and consequently improving Eustachian tube obstruction." (PMID 39595049, 2024).
Ewing sarcoma (1 paper, 2025). A small round cell tumor that lacks morphologic, immunohistochemical, and electron microscopic evidence of neuroectodermal differentiation. "In Ewing sarcoma, there were 21 significant relationships, including IL-4/IL-1β (r2 = 0.55, p = 0.00048), IL-4/IL-8 (r2 = 0.68, p = 0.0000047), CXCL14/IL-15 (r2 = 0.61, p = 0.00013), and CXCL5/CXCL12 (r2 = 0.64, p = 0.000030)." (PMID 41008853, 2025).
extrapulmonary tuberculosis (1 paper, 2023). A tuberculosis that occurs at body sites other than the lung. "Third, the small sample sizes of some subgroups (for example extrapulmonary tuberculosis group and plasma of the IL-4 group) may have led to reduced statistical potency." (PMID 37327256, 2023).
fertility disorders (1 paper, 2009). "In contrast, IL-1 Beta, IL-4, IL-5, IL-6 and IL-10 levels were found to be higher in CT-positive women with fertility disorders compared to CT-positive fertile women and controls (P < 0.05)." (PMID 19397832, 2009). "In contrast, IL-1β, IL-4, IL-5, IL-6 and IL-10 mRNA expression levels were significantly higher (P < 0.05) in cells obtained from CT-positive women with fertility disorders compared to other two groups." (PMID 19397832, 2009). "A significant finding of this study was the increased mRNA expression levels of IL-4, a classical Th2 marker, in cells obtained from CT-positive women with fertility disorders in comparison to the other two groups." (PMID 19397832, 2009). "IL-4 and IFN-γ spot forming cells (SFCs) were enumerated in inc-stimulated CD4+ T cells purified from cervical cells and PBMCs in CT-positive women with and without fertility disorders and controls." (PMID 19397832, 2009).
Flavivirus Infections (1 paper, 2023). Infections with viruses of the genus FLAVIVIRUS, family FLAVIVIRIDAE. "The significant differences in cytokine levels detected among ZIKV and DENV cases suggest that IL-4 and IL-10 may serve as differential immune indicators for acute ZIKV and acute DENV infections, respectively, when a flavivirus infection is considered." (PMID 37235332, 2023).
foot and mouth disease (1 paper, 2020). A viral infectious disease that results in infection in cattle and swine, has material basis in foot-and-mouth disease virus, which is transmitted by contaminated fomites, or transmitted by ingestion of food contaminated with infected meat or animal products. "(2009) showed that IFNγ, IL-10, and TNFa had peaked on week 3 in response to inactivated foot-and-mouth disease (FMD) vaccination while the remaining cytokines (IL-2, IL-4, IL-12p40) peaked on the 2nd week and decreased by the 3rd week." (PMID 33251155, 2020).
functional dyspepsia (1 paper, 2019). "A study in H. pylori-positive patients with functional dyspepsia investigated gastric inflammatory markers and ILs (IL-4, IL-6, IL-8, IL-10, and IFN-γ) following treatment with AXT from H. pluvialis." (PMID 31248010, 2019).
G6PD deficiency (1 paper, 2023). An X-linked genetic condition caused by alterations in the gene G6PD that result in moderately to severely decreased activity levels of the enzyme glucose-6-phosphate dehydrogenase. "G6PD deficiency has been associated with a proinflammatory state with over-expression of IL-8, IL-4, IL-5, and IL-9 cytokines, and increased chemotaxis of eosinophils and Th2 immune polarization." (PMID 37753082, 2023).
gallbladder cancer (1 paper, 2022). "Interestingly, inhibitory effects of IL4 and IL13 in human gallbladder cancer cells have hardly been investigated so far." (PMID 35207737, 2022).
gastric adenocarcinoma (1 paper, 2020). "In addition to LPS and IL-4 activation, THP-1 activated with conditioned medium (CM) from gastric adenocarcinoma (AGS) cells were morphologically similar to M2 macrophages." (PMID 33299895, 2020).
gastric cardia carcinoma (1 paper, 2022). A carcinoma that arises from epithelial cells of the cardia of stomach. "The study indicates that IL2 G-330T and IL4 T-168C promoter polymorphisms may contribute to the development of gastric cardia cancer in Chinese populations." (PMID 35884907, 2022).
gastric MALT lymphoma (1 paper, 2019). "In the murine model of Helicobacter felis (H. felis)-induced gastric MALT lymphoma, tumor-infiltrating CD4+ T cells co-express surface markers CD28 and CD69, and produce large quantities of IL-4, but not of interferon-gamma (INF-γ)." (PMID 30999581, 2019).
Gastric Metaplasia (1 paper, 2020). Intestinal metaplasia of the gastric mucosa is an intermediate precancerous gastric lesion in the gastric cancer cascade from chronic gastritis and atrophy to dysplasia and adenocarcinoma. "In addition, IL-4 immunoreactivity inversely correlated with the presence of gastric metaplasia or cancer and with degree of inflammation." (PMID 32512917, 2020).
gastrointestinal mucositis (1 paper, 2020). "While earlier studies conducted in mice models have established the microscopic features of gastrointestinal mucositis in 5-FU toxicity, recent reports have shown NF-κB and IL-4 to be critical mediators in this process." (PMID 33109089, 2020).
gastrointestinal stromal tumor (1 paper, 2015). "Tregs have been demonstrated to inhibit NK cells from gastrointestinal stromal tumors (GIST) by competing for IL-2 availability and secrete IL-4, indoleamine-2,3-dioxygenase (IDO)." (PMID 25972872, 2015).
Gaucher disease (1 paper, 2011). Gaucher disease (GD) is a lysosomal storage disorder encompassing three main forms (types 1, 2 and 3), a fetal form and a variant with cardiac involvement (Gaucher disease - ophthalmoplegia - cardiovascular calcification or Gaucher-like disease). "These analyses implicate IFNγ-regulated pro-inflammatory and IL-4-regulated anti-inflammatory networks in differential disease progression with implications for understanding the Gaucher disease course and pathophysiology." (PMID 21223590, 2011).
Gingival bleeding (1 paper, 2021). Hemorrhage affecting the gingiva. "The levels of IL-1α, IL-8, and IL-4 were higher in the gingival bleeding-high group than those in the gingival bleeding-low group." (PMID 34199256, 2021).
gliosarcoma (1 paper, 2023). A rare histological variant of glioblastoma (WHO grade IV) characterized by a biphasic tissue pattern with alternating areas displaying glial and mesenchymal differentiation (WHO). "In another attempt, authors immunized rats with the intradermal injection of IL-4-producing Rat 9L gliosarcoma cells." (PMID 36742134, 2023). "After the genetic modification of 9L gliosarcoma cells to express IL-4, syngeneic rats received the intracranial tumor injection of the-4 producing cancer cells, which almost resulted in the death of all the rats by tumor growth." (PMID 36742134, 2023).
gonococcal cervicitis (1 paper, 2007). "Gonococcal cervicitis in female sex workers has been shown to cause increases in interleukin-4 (IL-4), IL-6, interleukin-10 (IL-10), and TNFα, as well as a decline in CD4+ T cell counts." (PMID 17257430, 2007).
graft versus host disease (1 paper, 2020). An immune system disorder that occurs after allogeneic hematopoietic stem cell transplant and is a reaction of donor immune cells against host tissues. "At 3 wpi, IL-4 MSCs and MSCs had over-represented pathways suggesting autoimmune activation, including graft-versus-host disease and allograft rejection." (PMID 32563258, 2020).
Graves ophthalmopathy (1 paper, 2018). An autoimmune disorder of the EYE, occurring in patients with Graves disease. "Serum IL-4 expression has been observed to be closely associated with the disease activity of thyroid-associated ophthalmopathy and negatively correlated with TRAb levels." (PMID 29713343, 2018).
hantavirus infections (1 paper, 2021). "IL-4 has not been proposed as a key cytokine in hantavirus infections." (PMID 33815363, 2021).